DMRTB1 (DMRT like family B with proline rich C-terminal 1)
Synonyms: DMRT6
Tractability: No criterion of Open Targets' tractability assessment is met for any kind of drug.
Gene: Protein-coding gene on chromosome 1 (53,459,399 to 53,467,488, forward strand). Ensembl gene ENSG00000143006.
Subcellular location: Nucleus
Gene Ontology:
Molecular function: protein binding; DNA-binding transcription factor activity, RNA polymerase II-specific; RNA polymerase II cis-regulatory region sequence-specific DNA binding; double-stranded DNA binding; sequence-specific DNA binding
Biological process: regulation of transcription by RNA polymerase II; sex differentiation; regulation of DNA-templated transcription
Cellular component: chromatin; nucleus
Genetic constraint (gnomAD): Loss-of-function variants: 10 observed, 23.69 expected, observed/expected ratio (o/e) 0.42, 90% interval 0.26 to 0.72. The synonymous counts are far from expectation, so gnomAD's model fits this gene poorly and the ratio says little. Missense variants: 551 observed, 442.87 expected, observed/expected ratio (o/e) 1.24, 90% interval 1.16 to 1.34. Synonymous variants: 269 observed, 209.48 expected, observed/expected ratio (o/e) 1.28, 90% interval 1.16 to 1.42.
Homologues: Orthologues: chimpanzee DMRTB1 (97% identical), macaque DMRTB1 (89% identical), dog DMRTB1 (68% identical), mouse Dmrtb1 (52% identical), rat Dmrtb1 (51% identical), tropical clawed frog dmrtb1 (23% identical), Caenorhabditis elegans dmd-7 (13% identical), Caenorhabditis elegans dmd-9 (12% identical). Paralogues in human: DMRTA2 (24% identical), DMRTA1 (23% identical), DMRT3 (23% identical), DMRT2 (23% identical), DMRT1 (20% identical), DMRTC2 (15% identical), DMRTC1 (6% identical), DMRTC1B (6% identical).
Diseases named in the same sentence as DMRTB1 in open-access papers:
DMRTB1 is named in the same sentence as 5 diseases in open-access papers, as found by Europe PMC text mining. Sharing a sentence is not in itself a finding about the gene and the disease. The quoted sentences say what the papers report.
colorectal cancer (1 paper, 2020). A primary or metastatic malignant neoplasm that affects the colon or rectum. "DMRT like family B with proline rich C-terminal 1 (DMRTB1) mutation might relate to human colorectal cancer liver metastasis." (PMID 33083119, 2020).
infertile (1 paper, 2017). "DMRTB1 was a down-regulated common gene among MArrest, oligospermia and Ikbkap KO, GPR137B was common among teratospermia, Bcl6b and Pou3f1 KD, and LMNB2 was common among Bcl6b, Etv5 and Pou3f1 KD infertile mice." (PMID 29150651, 2017).
DMRTB1 also shares sentences with these, for which no sentence is quoted: gastric cancer (1 paper); oligospermia (1); teratospermia (1).